PIK3CA (phosphatidylinositol-4,5-bisphosphate 3-kinase catalytic subunit alpha)
Diseases named in the same sentence as PIK3CA in open-access papers (continued):
Sharing a sentence is not in itself a finding about the gene and the disease.
lung adenocarcinoma (continued). "According to their work PIK3CA was the second most common type of mutation with a frequency of >10% in majority of the cancers except ovarian serous carcinoma, renal clear cell cancer, lung adenocarcinoma and acute myeloid leukemia." (PMID 31905960, 2019). "However, PIK3CA mutation is more common in squamous-cell lung cancer than it is in lung adenocarcinoma." (PMID 26923333, 2016). "This study showed that the PIK3CA mutation could be detected in a small proportion (1.8%) of lung adenocarcinomas, but with high concomitant EGFR mutations." (PMID 27734950, 2016). "Only 15 of 23 patients harboring PIK3CA mutation had recurrence, which may affected the clinical efficacy analysis of PIK3CA mutation as predict and prognosis factor in lung adenocarcinoma." (PMID 27554588, 2016). "The frequency of PIK3CA mutation was around 2.8% in the Chinese patients of lung adenocarcinoma." (PMID 27554588, 2016). "However, because of heterogeneity and insufficient data of previous studies, no conclusion was observed for the frequency and prognosis of lung adenocarcinoma patients with PIK3CA mutation." (PMID 27554588, 2016). "PIK3CA mutations have been detected in approximately 2 % of lung adenocarcinomas." (PMID 26498038, 2015). "It suggested that PIK3CA mutation may be a predicator of poor prognosis for lung adenocarcinoma." (PMID 27554588, 2016). "The inferred edge from PIK3CA to CDH1 is consistent with the finding in lung adenocarcinoma that the inactivation of the PI3K pathway significantly reduced CDH1 expression." (PMID 36928529, 2023). "Genomic data analyses evidenced that EGFR and KRAS mutations, the most common aberrations in lung adenocarcinoma, are extremely rare in pure SCC, while alterations in the FGFR kinase family, PIK3CA, CDKN2A and RB1 pathways are common." (PMID 35743191, 2022). "The downregulation of miR-10a in chronic myeloid leukemia CD34+ cells increases USF2-mediated cell growth and increases the cisplatin resistance of lung adenocarcinoma circulating tumor cells via targeting PIK3CA in the PI3K/Akt pathway." (PMID 34062897, 2021). "Phosphatidylinositol-4,5-bisphosphate 3-kinase catalytic subunit alpha (PIK3CA) is one of the driving genes of lung adenocarcinoma." (PMID 34575576, 2021). "Our study reports a retrospective analysis on OS rates observed in patients with lung adenocarcinoma harboring somatic mutations either in EGFR and KRAS genes, or in less frequently studied genes, such as BRAF, PIK3CA, NRAS, and HER2 (niche mutations)." (PMID 32082488, 2020). "PIK3CA mutations are more commonly encountered in squamous NSCLC and seem to confer inferior prognosis in lung adenocarcinoma." (PMID 30744664, 2019). "1,760 lung adenocarcinoma patient blood samples were tested for analyzing mutations in EGFR, KRAS, NRAS, PIK3CA, HER2, BRAF and MET in cfDNA." (PMID 31749831, 2019).
lung adenocarcinoma (continued). "In cohort 1, the HS values of EGFR, KRAS, HER2, BRAF, and PIK3CA were calculated to estimate intratumor genetic heterogeneity in lung adenocarcinoma." (PMID 29518290, 2018). "The current study demonstrates PIK3CA mutant cells are prevalent as subpopulations within colon adenomas, colon adenocarcinomas, and lung adenocarcinomas." (PMID 28755461, 2017). "Here we report measurements of PIK3CA H1047R mutant fraction (MF) in normal colonic mucosa, normal lung, colonic adenomas, colonic adenocarcinomas, and lung adenocarcinomas." (PMID 28755461, 2017). "To evaluate the impact of PIK3CA mutations on EGFR TKI treatment responses, we focused on the 344 EGFR TKI-treated EGFR mutant lung adenocarcinoma patients with EGFR TKI-naïve tissue specimens." (PMID 27734950, 2016). "The driver genes involved in lung adenocarcinoma include KRAS, EGFR, ALK, and BRAF, and those implicated in lung squamous cell carcinoma (LSCC) include PIK3CA, FGFR1, EGFR, PDGFRA, and DDR2." (PMID 26373952, 2015). "Moreover, the synergistic effect of gefitinib and BYL719 was also confirmed in the 3D cell culture model, the in vivo model, as well as in the organoid model from a lung adenocarcinoma patient with EGFR, ErbB2, PIK3CA mutations and MET amplification." (PMID 37553597, 2023). "In addition, we detected the synergistic effect of gefitinib and BYL719 in organoids derived from a lung adenocarcinoma patient, harboring EGFR (L838V, L861Q), PIK3CA (H1047L), ErbB2 (D871N) mutations and MET amplification." (PMID 37553597, 2023). "Although it has been reported that 80% of lung adenocarcinoma with PIK3CA mutations is associated with EGFR mutations, no cases with pathogenic co-mutation of PIK3CA and EGFR were detected in our PPC cohort." (PMID 36243681, 2022). "The PIK3CA mutation rate in lung adenocarcinoma with acquired resistance to EGFR TKI is not higher than that in EGFR TKI-naïve tissue specimens (2.9% (6/207) vs. 1.8%; p = 0.344)." (PMID 27734950, 2016). "PIK3CA copy number gains are present are higher frequencies in SQCC than in lung adenocarcinoma." (PMID 27835880, 2016). "To understand the impact of PIK3CA mutation on clinical characteristics of advanced lung adenocarcinoma and the treatment response of EGFR TKIs, we examined PIK3CA and EGFR mutations from lung adenocarcinoma patients, and analyzed their clinical treatment outcomes." (PMID 27734950, 2016). "PIK3CA amplification was detected in 5 PIK3CA mutant samples (14.7%, 5/34) which was more prevalent in lung squamous cell carcinoma (4/12 for lung squamous cell carcinoma vs. 1/12 for lung adenocarcinomas, p = 0.042)." (PMID 24533074, 2014). "Additionally, available tumor DNAs were studied using the mentioned gene panel and the somatic variants found were in agreement with each cancer type, including a splicing variant in PTEN in the lung adenocarcinoma sample, and BRAF p.(V600E) and PIK3CA p.(G1049R) in thyroid cancer samples." (PMID 35227301, 2022). "The results of this study demonstrate that ATM‐ and PIK3CA‐positive and EGFR‐negative mutation status are strongly associated with high levels of TMB and have the potential to be predictive biomarkers of response to immune checkpoint inhibitors in lung adenocarcinoma patients." (PMID 35521981, 2022). "However, a recent study in young lung adenocarcinoma patients demonstrated the absence of PIK3CA gene mutations." (PMID 31905960, 2019).
lung adenocarcinoma (continued). "Levels of PIK3CA E545K mutation (codon 545 GAG→AAG) were measured in normal breast, colonic mucosa, lung, and thyroid DNA samples, as well as in DNA isolated from ductal carcinomas, colonic adenomas, colonic adenocarcinomas, lung adenocarcinomas, and papillary thyroid carcinomas." (PMID 28755461, 2017). "To understand the impact of PIK3CA mutations on clinical characteristics and treatment response to epidermal growth factor tyrosine kinase inhibitors (EGFR TKIs) of lung adenocarcinoma, we examined PIK3CA and EGFR mutations in lung adenocarcinoma patients, and analyzed their clinical outcomes." (PMID 27734950, 2016). "In conclusion, PIK3CA mutation may not be associated with primary resistance to EGFR TKI in lung adenocarcinoma patients." (PMID 27734950, 2016). "In conclusion, PIK3CA mutation may not be associated with primary resistance to EGFR TKI among lung adenocarcinoma patients." (PMID 27734950, 2016). "Whether the co-existing PIK3CA mutations cause primary resistance to EGFR TKI in lung adenocarcinoma was still not well studied." (PMID 27734950, 2016). "All of the identified co-occurring alterations in our study are well established based on data from previous studies, for example, the co-occurrence of PIK3CA, EGFR and KRAS in lung adenocarcinoma." (PMID 41153394, 2025). "The survival curve indicated that the expression of PIK3R1, PIK3CA, and AKT1 correlated with the mOS of lung adenocarcinoma (p < 0.05)." (PMID 36654811, 2023). "The PI3K protein family acted as critical roles in the lung adenocarcinoma, since the components of the PI3K protein family include PIK3C2B, PIK3CA, PIK3R1 and so forth were presented in the intersections." (PMID 28503373, 2017). "We observed no strong positive correlations for lung adenocarcinoma, providing evidence that the transcriptional effects of mutations in KRAS, EGFR, MET, NTRK1, and PIK3CA are distinct from each other." (PMID 29322935, 2017). "In addition, several other target oncogenes with potential prognostic roles in lung adenocarcinoma, including MET, PIK3CA, and RET, have also been described, and target agents are currently under development." (PMID 29290998, 2017). "We present the first portrait of clinically actionable alterations in lung adenocarcinoma of Indian origin that includes EGFR, KRAS, EML4-ALK, AKT1, PIK3CA, FGFR4 and ERBB2, similar to that identified in other ethnic groups, and an additional subset of patients with FGFR3 mutations." (PMID 27998968, 2017). "PIK3CA H1047R (codon 1047 CAT→CGT) MF was measured in normal colonic mucosa and lung DNA samples, as well as in DNA isolated from colonic adenomas, colonic adenocarcinomas, and lung adenocarcinomas." (PMID 28755461, 2017).
lung adenocarcinoma (continued). "In addition, several other target oncogenes with potential prognostic role in lung adenocarcinoma, including MET, PIK3CA, and RET, have also been described, and target agents are currently under evaluation." (PMID 26936516, 2016). "Some of the genes such as PIK3CA, TAF15, VAPB, Appl1, Rab5a, ARF4, and XIAP in Merged-module activate the PI3K-Akt pathway and are overexpressed in a manner similar to that of EGFR in lung adenocarcinoma." (PMID 23874428, 2013). "We took into consideration different rare mutations observed in BRAF, PIK3CA, HER2, and NRAS detected with a total frequency equal to 16.7% of patients with lung adenocarcinoma harboring somatic mutations, which is not a negligible prevalence if transposed to the entire population." (PMID 32082488, 2020).
non-small cell lung carcinoma (90 papers, 2011 to 2026). A group of at least three distinct histological types of lung cancer, including non-small cell squamous cell carcinoma, adenocarcinoma, and large cell carcinoma. "Non-small cell lung cancer (NSCLC) with PIK3CA mutations demonstrates significant challenges in treatment due to enhanced bone metastasis and immune checkpoint resistance." (PMID 40328748, 2025). "A KIF13A-PIK3CA fusion in sample AF0201 with non-small cell carcinoma was excluded because an out-of-frame mutation was found to eliminate the function of PIK3CA." (PMID 36033527, 2022). "PIK3CA mutation has been found in a large variety of human tumors, and a frequency of 2-7% in non-small-cell lung cancer (NSCLC) was observed according to previous studies." (PMID 32908885, 2020). "Here, we report our experience using next generation sequencing (NGS) to examine AKT1, BRAF, EGFR, ERBB2, KRAS, NRAS, and PIK3CA genes in 1006 non-small cell lung cancers in a clinical diagnostic setting." (PMID 29228562, 2017). "In an in vitro study, non-small-cell lung cancer (NSCLC) cells with PIK3CA mutations induced more effect responses of anti-proliferation and pro-apoptosis through the combined treatment of a dual PI3K/mTOR inhibitor and MEK inhibitor, compared to exclusive use." (PMID 40142329, 2025). "Initial implementation of this multiplexed SCODA mutation enrichment and detection assay focused on 46 mutations in 4 genes (BRAF, EGFR, KRAS, and PIK3CA), constituting a set of commonly encountered mutations of clinical relevance in colorectal and non-small cell lung cancers." (PMID 25575824, 2015). "While PI3K-targeted therapies suppress proliferation in PIK3CA-mutant non-small cell lung cancer (NSCLC), their clinical impact is limited due to compensatory activation of insulin receptor (IR) and insulin-like growth factor-1 receptor (IGF-1R) signaling." (PMID 41934916, 2026). "In non-small cell lung cancer, for instance, EGFR-mutant tumors with MET amplification, HER2 mutations, or PIK3CA alterations frequently develop resistance to EGFR inhibitors." (PMID 40076838, 2025). "Mutations of PIK3CA, PIK3R1, and PIK3R2 are frequently detected in small-cell lung cancer (SCLC), non-small-cell lung cancer (NSCLC), hepatocellular cancer, and ovarian serous cystadenocarcinoma." (PMID 37596643, 2023). "PIK3CA protein expression was correlated with stage II-IV disease and poor differentiation in non-small cell lung cancer." (PMID 33287350, 2020). "It regulates prothymosin-α (PTMA) and purine nucleoside phosphorylase (PNP) in bladder cancer and PIK3CA in NSCLC (Non-small cell lung carcinoma)." (PMID 30862091, 2019). "The principal mutations of EGFR, ALK, KRAS, BRAF, PIK3CA and HER2 were analyzed in 44 patients with non-small-cell lung cancer." (PMID 26968843, 2016). "Mutant Phosphatidylinositol 3-kinase CA (PIK3CA) stimulates the AKT pathway and promotes cell growth in several cancers, including ESCC and Non-small cell lung cancer (NSCLC) being associated in these cases with poor prognosis." (PMID 24422746, 2014). "In a large study evaluating the next-generation sequencing (NGS) of tumor tissues of 1144 non-small cell lung cancer (NSCLC) patients, PIK3CA mutations were found in 3.7% of patients, with the highest mutations in squamous cell carcinoma (8.9%) and less common in adenocarcinoma (2.9%)." (PMID 38396649, 2024).
non-small cell lung carcinoma (continued). "Although many molecular genetic studies indicate that there are some genetic mutations in non-small cell lung cancer (NSCLC), including EGFR, KRAS, PIK3CA, BRAF, ALK, DDR2, and PDGFRA, only a few studies have focused on the genetic events of salivary gland-type lung carcinomas." (PMID 26575266, 2015). "A number of molecular aberrations have been identified in non small cell lung cancer (NSCLC), including EGFR, BRAF, HER2 mutations, EML4-ALK, ROS1 and RET rearrangements in adenocarcinoma; FGFR mutations/amplifications, DDR2 or PIK3CA mutations in squamous cell carcinoma." (PMID 24898067, 2014). "Recently, it was reported that treatment of non-small cell lung carcinoma (NSCLC) with BEZ235 resulted in regression of PIK3CA-mutated but not K-RAS-mutated tumors." (PMID 23232026, 2012). "For example, alpelisib is currently in Phase III trials for treatment of PIK3CA driver mutations in cancers of the lung and other tissues, and a combination of dabrafenib and trametinib has clear efficacy in treatment of BRAF:V600E mutated non-small cell lung cancers." (PMID 31711466, 2019). "We investigate how Chiang Mai haze-derived PM2.5 impacts oxidative stress and gene expression in three non-small-cell lung cancer (NSCLC) cell lines: A549 (KRAS-mutant), NCI-H1975 (EGFR-mutant), and NCI-H460 (KRAS/PIK3CA-mutant)." (PMID 41600570, 2025). "In recent years, series of driver genes, such as EGFR, KRAS/NRAS, BRAF, PIK3CA, ALK and ROS1 and so on, have been found in non-small cell lung cancer (NSCLC) one after another with the development of molecular detecting technology." (PMID 29526181, 2018). "We aimed to investigate prevalence and prognostic role of SOX2, PIK3CA, FGFR1 and BRF2 gene gain in patients with surgically resected non-small cell lung cancer (NSCLC)." (PMID 24736592, 2014). "For instance, in non-small cell lung cancer patients with no available tumor biopsy, blood is the only source for detecting genetic alterations, including EGFR, KRAS, BRAF, PIK3CA mutations, and ALK rearrangements." (PMID 34359285, 2021). "The purpose of this study was to test genetic biomarkers used in clinical practice (EGFR, ALK) and candidate biomarkers identified by the French National Cancer Institute (KRAS, BRAF, PIK3CA, HER2) in patients with metastatic non-small-cell lung cancer for whom two tumor samples were available." (PMID 26968843, 2016). "In addition, a negative correlation between miR-1 and PIK3CA expression was detected in nearly 70% of non-small cell lung cancer specimens." (PMID 28537886, 2017). "In conclusion, the genetic mutations associated with PACC are different from those implicated in non-small cell lung cancer, and EGFR, KRAS, BRAF, ALK, PIK3CA, PDGFRA, and DDR2 may not be driver genes in PACC; we must identify other genes for targeted therapy against PACC." (PMID 26373952, 2015).